AKR1B1 (aldo-keto reductase family 1 member B)
Diseases named in the same sentence as AKR1B1 in open-access papers (continued):
Sharing a sentence is not in itself a finding about the gene and the disease.
diabetic retinopathy (39 papers, 2007 to 2025). "A related protein, AKR1B1, has been highlighted as a potential drug target following a proteomic analysis of patient vitreous samples, while genetic association studies find the AKR1B1 gene to be the most prominent risk gene in diabetic retinopathy." (PMID 41462614, 2025). "Genetic polymorphisms linked to the human AKR1B1 gene are associated with higher tissue levels of ALR2 and the development of advanced diabetic retinopathy." (PMID 32218152, 2020). "Reports have associated variations in the AKR1B1 gene with diabetic retinopathy increasing diabetic retinopathy risk." (PMID 32218152, 2020). "A meta-analysis study to investigate possible genetic associations with diabetic retinopathy, which incorporated reports published between January 1990 and August 2008, has revealed a significant variation in the AKR1B1 gene." (PMID 24286082, 2013). "This gene encodes aldo-keto reductase family 1 member B1, which is the rate limiting enzyme of the polyol pathway, one of the pathways implicated in the development of diabetic retinopathy." (PMID 24286082, 2013). "Similarly, several genes implicated in diabetic retinopathy – classically considered a retinal vasculopathy– were differentially expressed by RGCs (e.g AKR1B1, HS6ST3 and MPRIP), suggesting that a primary neuropathic process may also be involved." (PMID 32555229, 2020). "By identifying AKR1B1 as a key mediator of both metabolic and pro-inflammatory responses, we highlight a potential early therapeutic target in the management of diabetic retinopathy." (PMID 40724989, 2025).
breast carcinoma (31 papers, 2012 to 2026). "Methylation of PAX6, GSTP1, RASGRF2, and AKR1B1 promoters has been previously reported to be associated with lymph node metastasis of breast cancer." (PMID 36454866, 2022). "AKR1B1, a member of the aldo/keto reductase superfamily, was associated with the poor survival outcomes of basal-like breast cancer and can promote the occurrence and metastasis of cancer by activating epithelial-mesenchymal transition." (PMID 33292266, 2020). "This could be ascribed to their interaction with various breast cancer-associated protein targets such as CAs, AKR1B1, ADORA3, PTPN1, ESR2, and EGFR." (PMID 39482666, 2024). "In addition, proteomic analyses performed in breast cancer cells to explore the mechanisms underlying the AKR1B1 pro-oncogenic role indicate that AKR1B1 overexpression highly impacts cell metabolism." (PMID 37780210, 2023). "Furthermore, expression of ZEB1, a master regulator of EMT, in breast cancer cell line MDA‐231 has been shown to positively correlate with AKR1B1 expression, strengthening the association of AKR1B1 with EMT." (PMID 32633024, 2020). "Therefore, AKR1B1 associated with the maintenance of CSCs and is required for tumorigenicity and metastasis of breast cancer." (PMID 32633024, 2020). "This study aimed to investigate the clinical role of SMAD4 and AKR1B1 methylation as noninvasive prognostic biomarkers in breast cancer." (PMID 41760667, 2026). "In breast cancer cell lines, knockdown or inhibition of Akr1B1 decreases, whereas overexpression increases migration and invasion." (PMID 38283991, 2023). "Using an immunocompetent mouse model of breast cancer, we also found that AKR1B1 overexpression accelerates tumor growth and promotes metastasis." (PMID 37780210, 2023). "Studies in breast cancer cells support that siRNA knockdown of Akr1B1 retains some protein expression but results in an almost complete loss of PGF2α production and impairs migration and invasion." (PMID 38283991, 2023). "In this work, we showed that aldo–keto reductase AKR1B1 is a strong promoter of metastasis in vivo, and its upregulation exerts a marked effect on proteins related to metabolism in breast cancer cells." (PMID 37780210, 2023). "Together, these results show, for the first time, that AKR1B1 overexpression promotes metastasis in an orthotopic breast cancer model in vivo." (PMID 37780210, 2023). "Our work provides the first demonstration that AKR1B1 overexpression enhances metastasis from primary tumors, in a model of breast cancer in immunocompetent mice." (PMID 37780210, 2023). "For instance, in breast cancer cell lines, AKR1B1 was shown to cooperate with migration and invasion in vitro." (PMID 37780210, 2023). "AKR1B1 expression provides tumorigenic and metastatic advantage in basal-like breast cancer through activating the epithelia-mesenchymal transition and enhancing stem cell-like properties." (PMID 36816947, 2023). "It has been found that the expression level of AKR1B1 was connected with the EMT process of mammary cancer cells." (PMID 37751590, 2023). "(±)KU had a potential anticancer effect on breast cancer cells and showed potential for inhibiting AKR1B1 enzyme activity." (PMID 36552555, 2022). "The AKR1B1 gene can promote breast cancer development by activating the epithelial-to-mesenchymal transition (EMT) process and the observed missense variant is located in its functional domain." (PMID 35625741, 2022).
breast carcinoma (continued). "AKR1B1 is involved in the polyol pathway of glucose metabolism and has been reported to have the capacity to facilitate breast cancer, lung cancer, and colon cancer tumorigenesis via EMT." (PMID 35962452, 2022). "AKR1B1 is involved in the glucose transforming polyol pathway and has been reported to have the capacity to facilitate breast cancer tumorigenesis and metastasis via EMT process." (PMID 35962452, 2022). "Taken together, we concluded that (±)KU-bound AKR1B1 leads to the attenuation of cellular oxidative stress, as well as the aggressiveness of breast cancer cell migration." (PMID 36552555, 2022). "We recently reported that several molecules, aldo-keto reductase 1 member B1 (AKR1B1), fructose-1,6-biphosphatase (FBP1), and urine diphosphate–galactose ceramide galactosyltransferase(UGT8) were associated with breast cancer aggressiveness." (PMID 34746019, 2021). "In contrast, in another study, AKR1B1 was reported to be suppressed in breast cancer tissue in comparison with normal breast tissue." (PMID 32633024, 2020). "Epalrestat, an AKR1B1 inhibitor, significantly suppresses cancer stem cell properties, tumorigenicity, and metastasis of basal-like breast cancer cells through regulating the NF-κB pathway." (PMID 28978011, 2017). "In conclusion, SMAD4 and AKR1B1 methylation may serve as significant epigenetic markers affecting breast cancer prognosis, potentially indicating more aggressive disease and poorer outcomes in these patients." (PMID 41760667, 2026). "In basal-like breast cancer, an aggressive triple-negative subtype of mammary cancer, AKR1B1 is transcriptionally activated by Twist2 and sustains a positive feedback loop involving NF-κB activation via PGF2A, thereby reinforcing EMT and enhancing tumor invasiveness." (PMID 41154825, 2025). "On the other hand, high protein expression of AKR1B1 was observed in basal-like breast cancer, ovarian, pancreatic, and cervical cancer which may be attributed to post-transcriptional regulation or differences in the clinical status of the patients evaluated." (PMID 39055885, 2024). "AKR1B1 was found to be a direct transcriptional target of Twist2 in basal-like breast cancer." (PMID 39055885, 2024). "In addition, AKR1B1 mRNA and protein expression levels are highly correlated in breast cancer cell lines, suggesting that AKR1B1 protein levels are mainly regulated at the transcriptional level." (PMID 37780210, 2023). "In addition, levels of cancer stem cell markers were reduced upon AKR1B1 silencing in lung and breast cancer cell lines." (PMID 37780210, 2023). "In addition, the expression quantity and activity of AKR1B1 protein in human lung cancer, alcoholic liver disease, liver cancer, and breast cancer were significantly elevated and were closely related to tumor progression." (PMID 37751590, 2023). "In addition, the AKR1B1 overexpression by stable vector transfection on luminal breast cancer cells (T47D and MCF7) showed a contrary effect." (PMID 36552555, 2022). "However, ZP and EP (AKR1B1 inhibitors) showed a weak cytotoxic effect on all ovarian and breast cancer cell lines, especially on MCF7 and OVCAR3 cells, which a lack of AKR1B1." (PMID 36552555, 2022). "Moreover, AKR1B1 overall has shown more activity in red blood cells (RBCs) and tissues of breast cancer patients in all three grades of primary surgical and post‐chemotherapy samples." (PMID 32633024, 2020). "In addition to colorectal and breast cancers, the expression level of AKR1B1 has been studied in other cancers although some have shown over‐ or low‐ expression." (PMID 32633024, 2020). "Moreover, positive correlation and direct interaction of Twist2 and AKR1B1 have been indicated in breast cancer." (PMID 32633024, 2020).
breast carcinoma (continued). "The ROS generated by the presence of slaked lime in BQ may amplify AKR1B1 gene rendering TNFα induced proliferation of breast cancer cells." (PMID 22937096, 2012). "Thus, AKR1B1 methylation detected can become a marker for the early breast cancer diagnosis." (PMID 37751590, 2023). "Consequently, it has been shown that suppression of AKR1B1 inhibits the expression of RelA and Twist2 while its overexpression could induce RelA and Twist2 in various cell lines of breast cancer." (PMID 32633024, 2020). "The role of DNA methylation in the prognosis of breast cancer, particularly concerning small mothers against decapentaplegic 4 (SMAD4) and aldo-keto reductase family 1 member B1 (AKR1B1), remains largely unexplored." (PMID 41760667, 2026). "(±)KU was shown to bind to AKR1B1 and inhibit oxidative stress as well as the migration, EMT, and invasion of breast cancer cells." (PMID 39055885, 2024). "(−)KU mainly binds to colony-stimulating factor 1 receptor (CSF1R) to suppress breast cancer proliferation, while some trans-(−)-kusunokinin and trans-(+)-isoforms could inhibit intracellular proteins, such as heat-shock protein 90 alpha (Hsp90-α) and aldo-keto reductase family 1 member B1 (AKR1B1)." (PMID 36552555, 2022). "But TCGA data showed that RASGRF2, AKR1B1 and CRMP1 were low expressed in breast Cancer tissues, while RHOF was high expressed in breast Cancer tissues." (PMID 36454866, 2022). "In the breast cancer cell group, we found that TNBC cells (BT-549 and Hs578T cells) had higher AKR1B1 protein levels than luminal A subtype (MCF7 cells), and Hs578T cells showed the most distinct AKR1B1 protein." (PMID 36552555, 2022). "AKR1B1, RASGRF2, CRMP1, BNIP3, GSTP1, HOXA5 and PAX6 genes were methylated in ER-positive and HER2-negative breast cancer with ALNM." (PMID 36454866, 2022). "Moreover, in addition to highly methylated AKR1B1, RASGRF2 and CRMP1 gene promoters, BNIP3, GSTP1, HOXA5 and PAX6 gene promoters were also methylated in ER-positive and HER2-negative breast cancer with ALNM." (PMID 36454866, 2022). "Targeted bisulfite sequencing showed that the promoter methylation levels of AKR1B1, BNIP3, CRMP1, GSTP1, HOXA5, PAX6, and RASGRF2 were increased in ER-positive and HER2-negative breast cancers with ALNM, compared with ER-positive and HER2-negative breast cancers without ALNM." (PMID 36454866, 2022). "In addition, Cancer Genome Atlas (TCGA) data showed that RASGRF2, AKR1B1 and CRMP1 were low expressed in breast Cancer tissues, while RHOF was high expressed in breast Cancer tissues." (PMID 36454866, 2022). "Studies have found that the promoters of the AKR1B1 and RASGRF2 genes were highly methylated in breast cancer, which may serve as candidate methylation biomarkers for early breast cancer detection." (PMID 36454866, 2022). "Furthermore, in addition to highly methylated AKR1B1, RASGRF2 and CRMP1 gene promoters, BNIP3, GSTP1, HOXA5 and PAX6 gene promoters were also methylated in ER-positive and HER2-negative breast cancer with ALNM." (PMID 36454866, 2022). "The inhibitory effect of (±)KU against AKR1B1 resulted in the protection of glucose-induced cellular oxidation, the suppression of signaling molecules and an alteration in the EMT markers on Hs578T breast cancer cells." (PMID 36552555, 2022). "They found that AKR1B1 was expressed in basal‐like breast cancer (BLBC) at the protein level while it was absent in luminal cell lines." (PMID 32633024, 2020). "Additionally, aberrant methylation patterns in the AKR1B1, RASGRF2, CRMP1, BNIP3, GSTP1, HOXA5, and PAX6 genes have been observed in estrogen receptor (ER)-positive and HER2-negative breast cancer with axillary lymph node metastasis (ALNM), suggesting their potential as therapeutic targets." (PMID 40517231, 2025).
breast carcinoma (continued). "Accordingly, when we analyzed public databases, we found that breast cancer patients with high AK1B1 mRNA levels displayed a significant reduction in overall survival, with a survival probability of 0.807 and 0.872 for patients expressing high and low AKR1B1 mRNA, respectively (n = 2976)." (PMID 37780210, 2023). "Similarly, another study reported the up‐regulation of AKR1B1 in triple‐negative breast cancer and the basal subtype of breast cancer cell lines." (PMID 32633024, 2020). "Although studies measuring AKR1B1 expression could not clearly highlight its effect on breast cancer, several evidence suggest that AKR1B1 could play a significant role in breast cancer tumorigenesis and epithelial to mesenchymal transition (EMT)." (PMID 32633024, 2020). "Furthermore, in addition to highly methylated AKR1B1, RASGRF2 and CRMP1 gene promoters, BNIP3, GSTP1, HOXA5 and PAX6 gene promoters were also methylated in ER-positive and HER2-negative breast cancer with ALNM, which may serve as candidate methylation biomarkers." (PMID 36454866, 2022). "And compared with ER-positive and HER2-negative breast cancers without ALNM, the methylation levels of AKR1B1, RASGRF2, CRMP1, BNIP3, GSTP1, HOXA5, and PAX6 promoter were increased in ER-positive and HER2-negative breast cancers with ALNM." (PMID 36454866, 2022). "The results showed that compared with negative lymph node breast cancer tissues, RHOF promoter methylation levels were decreased in positive lymph node breast cancer tissues, while AKR1B1, RASGRF2, and CRMP1 gene promoter methylation levels were increased." (PMID 36454866, 2022). "Consequently, induced expression of AKR1B1 by Twist2 could regulate E‐cadherin which its suppression has been seen to induce migration and invasion regardless of EMT in breast cancer." (PMID 32633024, 2020).
lung cancer (24 papers, 2015 to 2025). A malignant neoplasm involving the lung. "Consistent findings in lung cancer and glioblastoma indicate that AKR1B1 has been shown to promote EMT via activation of the RhoA–ROCK2 pathway, thereby enhancing migratory and invasive behavior." (PMID 41154825, 2025). "The genes Fubp1, Cox6b1, Pon3, Iars2, Ctsd, and Akr1b1 have been previously shown to promote lung cancer proliferation." (PMID 39273313, 2024). "While AKR1B1 is significantly elevated in liver and lung cancer, it is more widely overexpressed in a range of malignancies and is associated with worse outcomes." (PMID 39055885, 2024). "Recently, AKR1B1 has been found to promote glutathione de novo synthesis to enhance acquired resistance to EGFR-targeted therapy in lung cancer." (PMID 36816947, 2023). "In lung cancer, high expression of AKR1B1 resulted in enhanced glutathione (GSH) synthesis and resistance to EGFR inhibitors in cell lines and xenograft models." (PMID 36463238, 2022). "Further knockdown of AKR1B1 in the A549 lung cancer cell line resulted in the reduction of EMT phenotype." (PMID 32633024, 2020). "Other DEPs including aldo-keto reductase family 1 member B1 (AKR1B1), cyclin-dependent kinase 2 (CDK2), death associate protein kinase-1 (DAPK1), peroxiredoxin-1 (PRDX1) and aldehyde dehydrogenase mitochondrial (ALDH2) are associated with lung cancer." (PMID 40088196, 2025). "In EGFR-mutant lung cancers, targeting aldo-keto reductase family 1 member B1 (AKR1B1), a key upstream regulatory protein of xCT that is upregulated in all resistant cell models, overcomes resistance to several TKIs by blocking cystine uptake and GSH accumulation." (PMID 39061847, 2024). "In addition, the gene AKR1B1 has been reported to be upregulated in mixed-lineage lung cancer cells." (PMID 37187731, 2023). "In lung cancer, AKR1B1 is a STAT3 activator that promotes glutathione de novo synthesis, eliminates ROS, protects cell from death, and reduces EGFR TKI drug sensitivity by upregulating the cystine transporter SLC7A11, it would be a therapeutic target for dealing with EGFR TKI resistance." (PMID 36512456, 2023). "AKR1B1 plays an important role in tumorigenesis and may serve as a candidate target for the treatment of lung cancer patients." (PMID 37187731, 2023). "Studies investigating the correlation between AKR1B1 and lung cancer revealed that the AKR1B1 expression change could be significant in the lung cancer metastasis." (PMID 37751590, 2023). "In summary, these data demonstrated that AKR1B1 could play important roles in the tumorigenesis of lung cancer." (PMID 35962452, 2022). "AKR1B1 is overexpressed in human tumors, such as those found in liver, breast, and lung cancer, and may play a important role in the development and progression of cancer." (PMID 24934327, 2015). "In addition, a study also showed that the expression of AKR1B1 was strongly correlated with EMT in lung cancer and colon cancer, during which process that tumor cells could obtain properties of cancer stem cells manifesting diverse plasticity." (PMID 35962452, 2022). "Furthermore, AKR1B1 could also play an important role in cancer progression, since higher AKR1B1 expression and activity were observed in breast, colon, and lung cancers." (PMID 32932589, 2020). "We highlighted specific proteins, including AKR1B1, CDK2, DAPK1, PRDX1 and ALHD2 with potential as biomarkers for radon-related lung cancer." (PMID 40088196, 2025). "The proteins such as AKR1B1, CDK2, DAPK1, PRDX1 and ALDH2 show potential as biomarkers or therapeutic targets for radon-related lung cancer after further validation." (PMID 40088196, 2025). "On the contrary, other research has indicated that the interaction between aldo-keto reductase family 1 member B1 (AKR1B1) and STAT3 results in the upregulation of SLC7A11, which promotes ferroptosis resistance in lung cancer." (PMID 38485916, 2024).
lung cancer (continued). "In lung cancer cell lines and PDX models, aldo-keto reductase family 1 member B1 (AKR1B1) promoted glutathione de novo synthesis by activating signal transducer and activator of transcription 3 (STAT3), leading to ROS scavenging and ultimately to EGFR-TKI drug resistance." (PMID 36911198, 2023). "Through our analysis, we also found other eight proteins (ACAT2, PSIP1, TCERG1, DPYSL5, TUBA1A, AKR1B1, ANP32E, and TXNDC17) that have been associated with other cancers, but not in lung cancer." (PMID 32351780, 2020). "In addition, AKR1B1 expression showed positive correlations with ZEB1 and lymph node involvement in lung cancer cell lines suggesting a role in EMT." (PMID 32633024, 2020). "Moreover, using immunohistochemistry (IHC), negative correlation was found between AKR1B1 and E‐Cadherin in tissues from resected non‐small cell lung cancer (NSCLC) patients." (PMID 32633024, 2020).